MID2 (midline 2)
Description:
E3 ubiquitin ligase that plays a role in microtubule stabilization. Mediates the 'Lys-48'-linked polyubiquitination of LRRK2 to drive its localization to microtubules and its proteasomal degradation in neurons. This ubiquitination inhibits LRRK2 kinase activation by RAB29.
Synonyms: FXY2; RNF60; TRIM1; MRX101; XLID101
Tractability: PROTAC: ubiquitination databases record sites on it.
Gene: Protein-coding gene on chromosome X (107,825,755 to 107,931,637, forward strand). Ensembl gene ENSG00000080561.
Subcellular location: Cytoplasm; Cytoplasm, cytoskeleton
Gene Ontology:
Molecular function: enzyme binding; microtubule binding; phosphoprotein binding; protein binding; protein homodimerization activity; transcription coactivator activity; ubiquitin protein ligase activity; zinc ion binding
Biological process: antiviral innate immune response; host-mediated suppression of symbiont invasion; positive regulation of autophagy; positive regulation of canonical NF-kappaB signal transduction; protein K48-linked ubiquitination; protein localization to microtubule; suppression of viral release by host; positive regulation of DNA-templated transcription; positive regulation of intracellular signal transduction; protein ubiquitination
Cellular component: cytoplasm; extracellular exosome; microtubule; cytoskeleton
Homologues: Orthologues: chimpanzee MID2 (100% identical), macaque MID2 (99% identical), chimpanzee MID2 (99% identical), rat Mid2 (99% identical), pig MID2 (99% identical), rabbit MID2 (99% identical), dog MID2 (95% identical), mouse Mid2 (93% identical), guinea pig MID2 (92% identical), tropical clawed frog mid2 (80% identical), zebrafish mid2 (78% identical). Paralogues in human: MID1 (69% identical), TRIM25 (17% identical), TRIM27 (17% identical), PML (17% identical), TRIM39 (16% identical), TRIM7 (16% identical), TRIM41 (16% identical), TRIM47 (16% identical), TRIM11 (16% identical), TRIM50 (16% identical), TRIM68 (15% identical), TRIM17 (15% identical), and 68 more.
Diseases named in the same sentence as MID2 in open-access papers:
MID2 is named in the same sentence as 26 diseases in open-access papers, as found by Europe PMC text mining. Sharing a sentence is not in itself a finding about the gene and the disease. The quoted sentences say what the papers report.
breast carcinoma (10 papers, 2019 to 2024). "In breast cancer, it was observed that MID2 expression exhibited a notable upregulation and a positive correlation with stage, Ki67 protein expression, and poor prognosis, promoting cancer cell proliferation." (PMID 39268080, 2024). "It is intriguing to investigate the effects of MID2 on breast cancer via the JAK-STAT signaling pathway." (PMID 37760252, 2023). "In breast cancer, MID2 is upregulated and mediates tumor chemoresistance." (PMID 38549156, 2024). "Similarly, a high level of MID2 expression was significantly correlated with breast cancer progression." (PMID 37760252, 2023). "It has shown that MID2 was overexpressed in breast cancer and might act as a biomarker for prognosis." (PMID 37760252, 2023). "A recent study revealed that MORC4 might confer increased chemoresistance to breast cancer cells via STAT3-mediated MID2 upregulation." (PMID 37760252, 2023). "A recent study has revealed MORC4 could induce the expression of MID2 by recruiting STAT3 to MID2’s promoter region, leading to enhancement of the chemo-resistance to breast cancer cells." (PMID 37760252, 2023). "Similarly, high level of MID2 expression was significantly correlated with breast cancer progression." (PMID 30941058, 2019). "In addition, MORC4 recruits STAT3 to the MID2 promoter and drives MID2 expression in luminal A/B breast cancer cells, which enhances the chemoresistance of breast cancer, indicating that MORC4 may be a therapeutic target for luminal A/B breast cancer therapy." (PMID 34839357, 2021). "MID2, as a promoter of STAT3, is interacted with protein MORC4, which regulates DNA damage response and gene transcription in breast cancer." (PMID 36925638, 2023). "Overexpression of MID2 and DBN1 which are regarded as the top up-regulated hub genes in GSE76092 dataset is related to chemoresistance in breast cancer and leukemia, respectively." (PMID 37535601, 2023).
Intellectual disability (6 papers, 2016 to 2025). "Research has unveiled the biological significance of MID2, which is associated with conditions such as intellectual disability." (PMID 38153584, 2024). "Another CNV encompassing gene associated with an intellectual disability is partial duplication of the MID2 gene, which was revealed in male patient GC034808." (PMID 36980952, 2023). "In fact, TRIM18/MID1 is mutated in a developmental disorder characterized by midline defects, X-linked Opitz Syndrome (XLOS, OMIM 300000), and TRIM1/MID2 is responsible for another X-linked form of intellectual disability (MRX101, OMIM 300928)." (PMID 35053362, 2022). "Furthermore, an H-DNA of 263 bps lies entirely within the gene MID2, which is associated with Intellectual Disability." (PMID 40041207, 2025). "One well-known disorder associated with MID2 is Opitz G/BBB syndrome type 1 (FG syndrome), characterized by developmental and intellectual disabilities." (PMID 38153584, 2024).
Opitz Syndrome (3 papers, 2018 to 2023). "MID2 is associated with Opitz syndrome, a primary midline development disease characterized by congenital facial malformation, abnormalities of the central nervous system (including motor skill defects and developmental delay), and congenital heart defects." (PMID 36978128, 2023).
developmental delay (2 papers, 2023). "A missense mutation in MID2 was described in a large Indian family with global developmental delay and minor facial features." (PMID 36980952, 2023). "Previously, a duplication overlapping MID2 was reported in a boy with FG syndrome, an X-linked multiple congenital anomalies syndrome (OMIM 300581), who had hypotonia and developmental delay." (PMID 36980952, 2023).
FG syndrome (2 papers, 2023 to 2024). "Recently, an Xq22 duplication including MID2 was described in a patient whose phenotypic features were not consistent with FG syndrome." (PMID 36980952, 2023).
Parkinson disease (2 papers, 2022 to 2024). A progressive degenerative disorder of the central nervous system characterized by loss of dopamine producing neurons in the substantia nigra and the presence of Lewy bodies in the substantia nigra and locus coeruleus. "While these findings remain observational, it is of potential interest that two TRIM members with MT-binding capacity (TRIM1/MID2 and TRIM9/SPRING) have been linked to Parkinson’s disease." (PMID 39205302, 2024).
viral infections (2 papers, 2013 to 2023). "Taken together, these results revealed that MID2 is a multifunctional protein, associated with development, innate immunity, cancer, viral infections, and disease." (PMID 37760252, 2023). "Midline2 (MID2) is widely involved in development, innate immunity, cancer, viral infections, and disease, but its role in pigs remains unexplored." (PMID 37760252, 2023).
cryptorchidism (1 paper, 2021). The failure of one or both testes of a male fetus to descend from the abdomen into the scrotum during the late part of pregnancy. "We speculate that MID2 may play a role in the development and could be responsible for the heart defect (aortopulmonary collaterals) or genital anomalies (micropenis, cryptorchidism) or kidney defect (duplicated renal pelvis) and facial dysmorphism, including hypertelorism, in our family." (PMID 34777475, 2021).
ovarian carcinoma (1 paper, 2023). A malignant neoplasm originating from the surface ovarian epithelium. "Recent research has demonstrated that MID2 plays an essential role in breast and ovarian cancer progression and can be a potential cancer biomarker." (PMID 36895786, 2023).
X-linked intellectual disabilities (1 paper, 2017). "MID2 leads to misregulation of microtubule organization and the downstream disease pathology associated with X-linked intellectual disabilities." (PMID 28934224, 2017).
cancer (9 papers, 2019 to 2024). A tumor composed of atypical neoplastic, often pleomorphic cells that invade other tissues. "Previous literatures report the association between DNA methylation in CpG islands and EMT in diseases, which implied that the effects of MID2 on cancer progress may be associated with DNA methylation." (PMID 38549156, 2024). "Another study showed that MID2 mainly regulates cell division by ubiquitinating and degrading the microtubule-associated protein astrin, which may be an important pathway for promoting cancer cell proliferation." (PMID 39268080, 2024). "Our findings suggest that MID2 has the great potential to be explored as the maker of immune checkpoint blockade response and cancer stemness." (PMID 36895786, 2023). "We found that the expression level of the MID2 gene correlated positively with that of all immune checkpoints and cancer stemness." (PMID 36895786, 2023). "Other genes such as VPS13C, ANKDD1B, and MID2 have been rarely investigated in drug resistance‐related cancer research." (PMID 34026427, 2021). "The previous studies using PLATO have identified a set of TRIM proteins (TRIM1/MID2, TRIM18/MID1, TRIM54 and TRIM55) as cancer autoantigens of paraneoplastic neurological disorder (PND)." (PMID 31494268, 2019). "Some genes, which appeared to be virtually switched off in B4GALNT2-expressing cells, are involved in the basic properties of cancer cells, such as stemness (SOX2, ROR1), epithelial to mesenchymal transition (EMT) (NID1, ALX1), and growth (FAM110B, PEG10, MID2)." (PMID 32290493, 2020).
tumor (7 papers, 2022 to 2024). "Taken together, these data suggested that MID2 plays an important role in tumor development and X-linked developmental disorders." (PMID 37760252, 2023). "In addition, we found that the expression of MID2 in the prognosis model increase along with tumor stage progression and was significantly associated with EMT function." (PMID 38549156, 2024). "MID2 plays an important role in tumor development, interacting physically with the breast cancer 1 early-onset gene (BRCA1)." (PMID 37760252, 2023). "Additionally, because EMT is a critical regulator pathway of tumor invasiveness, we assessed the effect of MID2 on cell migration and invasion using transwell assays." (PMID 38549156, 2024). "Since MID2 has been involved in human tumor development and acts as a prognostic biomarker, pMID2 might serves as a neoplastic biomarker in tumors of pigs." (PMID 37760252, 2023). "The difference analysis of 41 paired samples of TCGA-COAD showed that the mRNA levels of ARHGAP4, SIAH2, TRIM45, and WDR72 were significantly upregulated in the tumor group, while MID2 and UBE2D2 showed no statistical difference." (PMID 39268080, 2024). "Since MID2 is activated at mitotic exit, we decided to focus our analysis on CUL9 and FBXL10, which have been shown to prevent genome instability, aneuploidy and spontaneous tumour development in cells and mice." (PMID 35469017, 2022).
genetic disorder (2 papers, 2024). "MID2, which was firstly identified as a causative gene of the X-linked form of a genetic disorder, is a ubiquitin-conjugating E3 enzyme and can regulate cytokinesis." (PMID 38549156, 2024). "Mutations or abnormalities in the MID2 gene have been associated with various genetic disorders." (PMID 38153584, 2024).
MID2 also shares sentences with these, for which no sentence is quoted: colon cancer (2 papers); X-linked Opitz G/BBB syndrome (2); colorectal cancer (1); COVID-19 (1); dementia (1); kidney cancer (1); leukemia (1); lung carcinoma (1); melanoma (1); Micropenis (1); neuroblastoma (1); rectal cancer (1); Tinnitus (1).